CKS1B (CDC28 protein kinase regulatory subunit 1B)
Diseases named in the same sentence as CKS1B in open-access papers (continued):
Sharing a sentence is not in itself a finding about the gene and the disease.
tumor (continued). "Re-expression of CKS1B induces much more and large tumor spheres, suggesting re-expression of CKS1B increases stemness ability of miR-1258 transfected HCC cells." (PMID 27270326, 2016). "The tumor sphere formation results also showed that re-expression of CKS1B significantly promotes sphere formation ability of miR-1258 transfected HCC cells." (PMID 27270326, 2016). "Mechanistic investigations reveal that a miR-197-mediated CKS1B/STAT3 axis exerts tumor progression regulated by various oncogenic genes (Bcl-2, c-Myc, and cyclin D1), and PD-L1 is a putative biomarker of this axis." (PMID 25597412, 2015). "In this study, we demonstrated that the miR-197/CKS1B/STAT3-mediated signaling drives tumor PD-L1 expression, allowing it to function as a biomarker for this cascade in NSCLC." (PMID 25597412, 2015). "Additionally, these cells exhibit specific upregulation of CEP55, PBK, BIRC5, STMN1, MT2 A, and CKS1B, all of which are related to tumor inflammatory responses." (PMID 40524208, 2025). "This supports the idea that CKS1B and its co-expressed genes may interact in a network that influences tumor cell behavior and malignancy." (PMID 40165937, 2025). "Similar to luminal cluster 2 in primary tumour, cluster 3 in lung mets, was enriched in a proliferation gene signature (Ran, Cks1b, and Cks2), whereas cluster 2 (homologous to cluster 3 in primary tumour), expressed a mesenchymal-like gene set (Col18a1, Vcam1, Col1a1, Vim, Sparc)." (PMID 38238426, 2024). "Studies suggest that heightened expression of CKS1B may be correlated with abnormal proliferation, malignant transformation, invasiveness and prognosis of tumour cells." (PMID 38946232, 2024). "There was a clear correlation between CKS1B+ neoplasm and the efficacy of immunotherapy, leading us to reasonably hypothesize that CKS1B+ neoplasm could be a potential target for LUAD immunotherapy." (PMID 38946232, 2024). "Notably, we found a significant correlation between CKS1B+ tumour cell abundance and treatment response, as well as stemness potential." (PMID 38946232, 2024). "As such, CKS1B expression levels directly correlated with acute tumor reduction in vivo (R=-0.446)." (PMID 35731890, 2022). "Furthermore, CIBERSORT analysis showed that there was a strong correlation between CKS1B expression and tumor immune cells infiltration." (PMID 36405738, 2022). "Here, we show that CKS1B is over-expressed in S-CIN tumours, which might be important for the stratification of patients." (PMID 35326573, 2022). "Considering the upregulation of CKS1B was associated with a variety of tumor progression and prognosis, we speculated CKS1B might be involved in tumor immune response." (PMID 34845438, 2021). "Tumor cases were divided into high CKS1B expression group and low CKS1B expression group." (PMID 34845438, 2021). "The expression of CKS1B was mainly localized in the nucleus of tumor cells." (PMID 34925510, 2021). "Therefore, knowledge of cell cycle and the expression of related genes represented by CKS1B can ascertain the essence of tumor development." (PMID 34925510, 2021). "Furthermore, CKS1B accelerates chemotherapeutic resistance in many types of cancers, while a decrease in CKS1B makes these tumor cells sensitive to chemotherapeutic drugs, suggesting that CKS1B is a promising treatment target in cancers." (PMID 33102238, 2020). "In addition, experiments have shown that miR-1258 exerts a tumor-suppressive effect through immediately downregulation of the oncogenic CKS1B gene in CRC." (PMID 33102238, 2020).
tumor (continued). "Considering the highly increased levels of CKS1B and decreased expression of miR-1258 in tumors from CRC patients, these findings suggest that miR-1258 may play tumor-suppressive roles by targeting CKS1B expression in CRC." (PMID 31717435, 2019). "Taken together, these results indicate that miR-1258 may play tumor-suppressive roles in CRC through negatively regulating oncogenic CKS1B gene expression." (PMID 31717435, 2019). "Furthermore, miR-197/CKS1B/STAT3-mediated network regarded the tumor expression of PD-L1 as a biomarker of this cascade, and the biological interaction between PD-L1 and chemoresistance occurred through this microRNA regulatory cascade." (PMID 30290817, 2018). "Since this target emerged from our in silico analyses and has major implications in tumor drug response and patient outcome, we determined whether CKS1B was copy-gained." (PMID 25995187, 2015). "Our discoveries suggest that the miR-197/CKS1B/STAT3-mediated network can drive tumor PD-L1 expression as a biomarker of this cascade, and miR-197 replacement therapy may be a potential treatment strategy for chemoresistant NSCLC." (PMID 25597412, 2015). "Furthermore, the relationship between CKS1B and tumor immune microenvironment was also discussed." (PMID 36405738, 2022). "Collectively, our data strongly indicate that FOXM1 upregulates CKS1B expression transcriptionally in PDAC cells and CKS1B is instrumental in mediating FOXM1-driven tumor proliferation, migration, and stemness, thereby promoting tumor progression." (PMID 39897042, 2025). "FBXW7 was the most recurrently observed F-box protein among K562 hits, paired with many cell cycle related proteins (e.g. CDK2AP1, CDK4, CDKN1A, CKS1B), consistent with the known role of FBXW7 as a tumor suppressor." (PMID 39919746, 2025). "CKS1B played a crucial role in promoting cell proliferation, migration, and stemness in PDAC, ultimately contributing to tumor progression and chemoresistance." (PMID 39897042, 2025). "CKS1B/STAT3 signaling promotes PD-L1-mediated tumor progression in PTC, with coordinated upregulation of CKS1B and PD-L1 observed in cell models at both mRNA and protein tiers." (PMID 40861443, 2025). "CKS1B+ neoplasm, C16orf89+ neoplasm, CST6+ neoplasm, H2AC6+ neoplasm and MTND2P13+ neoplasm all demonstrate heightened tumour stemness." (PMID 38946232, 2024). "CKS1B+ neoplasm, CST6+ neoplasm and MTND2P13+ neoplasm are more prevalent in advanced LUAD, while DLX5+ neoplasm is more common in early‐stage LUAD." (PMID 38946232, 2024). "In fact several genes such as CKS1B, PSMD4, IL6R, MCL1 involved in proliferation and survival of tumour cells, mechanisms of chemo refractoriness, and alteration of the microenvironment are located in the 1q21 region." (PMID 36755858, 2022). "The patient we presented was initially diagnosed with IgD-λ RRMM, accompanied by rare complex karyotypes, CKS1B (1q21) and CDKN2C (1p32.3) genetic abnormalities, and high tumor burden." (PMID 34003300, 2022). "Herein, we determined that in LUAD cells, ASF1B can indirectly regulate CKS1B, POLE3, and DHFR expression, and we found it positively correlated with the expression of these genes in most tumor and normal tissue samples." (PMID 34568067, 2021). "In this study, we found for the first time that miR-1258 plays a tumor-suppressive function in CRC, as its increased expression resulted in the downregulation of the oncogene CKS1B." (PMID 31717435, 2019). "A similar analysis in BRCA1 vs BRCA2 tumours highlighted increase in PPI co-expression around the mitotic regulators CDK1, CDC20 and CKS1B and the histone deacetylases HDAC1 and HDAC6; these are known drug targets for which inhibitors have been developed." (PMID 25521701, 2014). "Core promoters with adjacent regions of the human genes CDC6, POLD1, CKS1B,MCM2, and PLK1 were cloned into a pGL3 vector in front of the Photinus pyrailsgene Luc in order to study the tumor specificity of the promoters." (PMID 24303203, 2013).
tumor (continued). "The data identified several kinases that are up-regulated in tumor cells, including; MET, PFTK1, BUB1, CKS1B, EIF2AK2, and NEK2." (PMID 22280838, 2012). "Notably, CKS1B+ neoplasm significantly enriches pathways related to cell proliferation, while S100A2+ neoplasm is markedly enriched in angiogenesis and epithelial–mesenchymal transition pathways." (PMID 38946232, 2024). "What’s more, we evaluated the connections between CKS1B expression and neoantigens, MSI, and TMB, which may anticipate the treatment effectiveness of tumor immunotherapy." (PMID 36405738, 2022). "The cell cycle (Cycling) program was characterized by high expression of genes involved in cell proliferation (e.g., CENPW, CKS1B, and BIRC5) and presented activation of the E2F targets, G2M checkpoint and MYC targets pathways, suggesting tumor cell proliferation." (PMID 34489433, 2021). "CKS1B expression was negatively regulated by miR-1258, which led to the suppression of cell proliferation, migration, and tumorigenicity in CRC cells, indicating that miR-1258 functions as a tumor suppressor in CRC." (PMID 31717435, 2019). "Besides influencing cell growth and survival through regulation of p27Kip1, silencing of CKS1B is also known to induce cell death and inhibit growth of tumour cells through mechanisms that are independent of p27Kip1and SKP231,32." (PMID 30937183, 2019). "Heat shock-activated HSF1 is mainly responsive to the expression of heat shock proteins, while activation of HSF1 in tumor tissues is predominantly responsible for controlling the expression of non-heat shock proteins, e.g. CKS2, LY6K, RBM23, CCT6A, CKS1B, ST13 and EIF4A2." (PMID 25199534, 2014).
cancer (41 papers, 2010 to 2025). A tumor composed of atypical neoplastic, often pleomorphic cells that invade other tissues. "Our study also highlighted the importance of CKS1B in regulating multiple signaling pathways associated with cancer." (PMID 40165937, 2025). "Cyclin-dependent kinase regulatory subunit 1B (CKS1B), a key regulator of the cell cycle, has been implicated in various human cancers." (PMID 40165937, 2025). "Conversely, c-Fos overexpression decreased the proportion of cells at G2/M phase compared with that in NQO1-deficient RKO/pshNQO1 and MDA-MB-231/pCont cancer cells, and this effect was mitigated by knockdown of CKS1B." (PMID 36793872, 2023). "To better understand the involvement of NQO1 in cell cycle progression, we investigated gene expression in RKO/pshCont and RKO/pshNQO1 cells, demonstrating that NQO1 increased transcription of CKS1B encoding the CKS1 protein in cancer cells." (PMID 36793872, 2023). "Overexpression of c-Fos in NQO1-deficient cancer cells enhanced radioresistance, an effect that was blunted by siRNA-mediated knockdown of CKS1B." (PMID 36793872, 2023). "As a regulatory subunit of cyclin kinase, CKS1B promotes cancer development and is associated with poor prognosis in multiple cancer patients." (PMID 36405738, 2022). "CKS1B has recently been linked to cancer drug resistance and was discussed as a new therapeutic target." (PMID 35326573, 2022). "A large number of studies have shown that CKS1B is associated with the pathogenesis of many human cancers and closely related to drug resistance." (PMID 33102238, 2020). "Here, we describe the current understanding of the cellular functions of CKS1B and its underlying mechanisms, summarize a recent study of CKS1B as a target for cancer treatment and discuss the potential of CKS1B as a therapeutic target." (PMID 33102238, 2020). "Increasing evidence from next-generation sequencing (NGS) data has demonstrated CKS1B upregulation in various cancers, and its overexpression was associated with poor prognosis and high aggressiveness in hepatocellular carcinoma and multiple myeloma." (PMID 31717435, 2019). "Copy gain and increased expression of CKS1B are associated with poor patient outcome and drug-resistant cancer (4, 20, –, 23)." (PMID 26755726, 2016). "Interestingly, CKS1BP7, a non-SVA-associated copy, is expressed in about a third of breast cancer tumors, and overexpression of the CKS1B parent gene is associated with aggressive progression and poor prognosis in a number of cancers." (PMID 41199327, 2025). "Given the crucial role of CKS1B in cell cycle regulation and its association with poor prognosis in several cancers, we hypothesized that CKS1B expression may serve as a prognostic biomarker for the early diagnosis and treatment of LUAD and LUSC." (PMID 40165937, 2025). "The CKS1B gene, in this context, encodes a critical regulatory subunit that plays a pivotal role in modulating the cell cycle, underscoring its potential significance in cancer biology and therapy." (PMID 38946232, 2024). "Taken together, the data indicate that CKS1B participates in the transcriptional regulation of an orchestrated set of genes that are associated with cell cycle progression and are thus linked to cancer cell proliferation and migration." (PMID 31717435, 2019). "A comparison of gene expression profiles of FACS-sorted double positive keratinocytes isolated from UV-treated WT and TG mice indicated increased expression of Pes1, Rad21, Tfdp1, and Cks1b genes in TG mice linked to cell transformation, invasion, and metastasis of cancer cells." (PMID 23738074, 2013). "Overall, the findings showed that the CKS1B gene is significantly upregulated in LC tissues as compared to normal tissues and other cancer cells." (PMID 40165937, 2025). "CKS1B is substantially upregulated in various cancer cells, including LC, according to 56 studies out of 452 retrieved datasets." (PMID 40165937, 2025).
cancer (continued). "GEPIA2 results also indicate a similar pattern of CKS1B upregulation in 33 different types of cancer cells including LUAD and LUSC." (PMID 40165937, 2025). "CKS1B is overexpressed in various cancers, including LUAD and LUSC, according to a review of GENT2 databases using HG-U133pLUS 2 and HG-U133A platforms (Cii)." (PMID 40165937, 2025). "Cyclin-dependent kinase regulatory subunit 1B (CKS1B) has emerged as a key player in cell cycle regulation and cancer progression." (PMID 40165937, 2025). "Lastly, the role of CKS1B in the regulation of cancer cell stemness remains to be conclusively determined and warrants additional experimental corroboration through in vivo and in vitro investigations." (PMID 39046884, 2024). "Conversely, in vitro experiments revealed CKS1B knockdown significantly impaired aggressive cancer phenotypes like proliferation, migration, and invasion of LUAD cells, highlighting its pivotal role." (PMID 39046884, 2024). "To further identify the transcription factor(s) that mediate CKS1B expression in cancer cells, we analyzed gene expression in NQO1-containing (RKO/pshCont) and NQO1-deficient (RKO/pshNQO1) cells." (PMID 36793872, 2023). "Similar NQO1-mediated CKS1B induction was observed in other cancer cell lines, including A549 (lung), MIA PaCa-2 (pancreas), PC3 (prostate), and U87-MG (brain) cell lines." (PMID 36793872, 2023). "siRNA-mediated knockdown of c-Fos (sic-Fos transfection) increased the proportion of cells at G2/M phase in NQO1-expressing cancer cells compared with that in the siCont-transfected group, an effect that was rescued by reintroduction of CKS1B." (PMID 36793872, 2023). "Taken together, our results suggest that NQO1 regulates CKS1B mRNA transcription and cell cycle progression at the G2/M phase in cancer cells through induction of c-Fos expression." (PMID 36793872, 2023). "CKS1B is crucial for the function of cyclin dependent kinases and for progression through cell cycle in cancer cells." (PMID 37963971, 2023). "From a mechanistic point of view, ASF1B indirectly regulated CKS1B to mediate growth, apoptosis, and cell cycle progression in cancers." (PMID 35480879, 2022). "Based on information obtained from the TCGA database, the gene expression levels of CKS1B in various human cancers were compared with those found in normal tissues." (PMID 36405738, 2022). "In the pan-cancer dataset, an investigation of the connection between the CKS1B expression and patients’ prognoses was carried out." (PMID 36405738, 2022). "CKS1B, a member of Cks/Suc1 family, is involved in the regulation of cell cycle and chemotherapeutic resistance in cancers." (PMID 34820377, 2021). "Recently, more and more scholars have discovered that CKS1B is closely related to the occurrence and development of malignant tumors." (PMID 34845438, 2021). "ASFB1 expression was also associated with POLE3, CKS1B, and DHFR expression in most normal tissues and in many cancers including LUAD (R>0.4, p<0.05)." (PMID 34568067, 2021). "At the same time, we investigated the potential mechanisms of CKS1B in pathogenesis and clinical prognosis of different cancers in terms of gene expression, gene alteration, patient survival, DNA methylation, immune infiltration, and pathway enrichment." (PMID 34845438, 2021). "In this study, TCGA, ONCOMINE, and other databases were used for the first time to conduct a pan-cancer analysis of CKS1B." (PMID 34845438, 2021). "Previously, it was demonstrated that upregulation of the oncogenic protein CKS1B promotes cell growth, invasion, metastasis, and chemoresistance and that CKS1B expression is dysregulated in various cancer types." (PMID 31717435, 2019). "Taken together, our data demonstrate that miRNAs modulate CKS1B gains and expression in vitro and show an association in vivo, which provides another mechanism for increased levels of this oncogene that may contribute to resistance to cisplatin and other drugs in cancer." (PMID 26755726, 2016).